RNU6-1308P (RNA, U6 small nuclear 1308, pseudogene)
Gene: Small nuclear RNA gene on chromosome 3 (107,007,568 to 107,007,670, forward strand). Ensembl gene ENSG00000252626.
Homologues: Orthologues: chimpanzee U6 (100% identical), macaque U6 (98% identical), rat U6 (80% identical), mouse Gm26011 (66% identical). Paralogues in human: RNU6-1060P (83% identical), RNU6-1152P (83% identical), RNU6-166P (83% identical), RNU6-41P (83% identical), RNU6-820P (83% identical), RNU6-974P (83% identical), RNU6-15P (82% identical), RNU6-19P (82% identical), RNU6-203P (82% identical), RNU6-211P (82% identical), RNU6-259P (82% identical), RNU6-317P (82% identical), and 1285 more.